GNPAT (glyceronephosphate O-acyltransferase)
Description:
Dihydroxyacetonephosphate acyltransferase catalyzing the first step in the biosynthesis of plasmalogens, a subset of phospholipids that differ from other glycerolipids by having an alkyl chain attached through a vinyl ether linkage at the sn-1 position of the glycerol backbone, and which unique physical properties have an impact on various aspects of cell signaling and membrane biology.
Synonyms: DAP-AT; DAPAT; DHAPAT; RCDP2
Tractability: Antibody: UniProt places it where antibodies can reach, with medium confidence. PROTAC: ubiquitination databases record sites on it; its protein half-life has been measured; a small molecule that binds it is known.
Target class: Enzyme; Transferase
Gene: Protein-coding gene on chromosome 1 (231,241,196 to 231,277,973, forward strand). Ensembl gene ENSG00000116906.
Subcellular location: Peroxisome membrane
Subcellular location (Human Protein Atlas): Cell Junctions; Vesicles
Pathways (Reactome):
Metabolism: Plasmalogen biosynthesis; Synthesis of PA
Protein localization: Peroxisomal protein import
Gene Ontology:
Molecular function: glycerone-phosphate O-acyltransferase activity; acyltransferase activity; catalytic activity
Biological process: ether lipid biosynthetic process; phosphatidic acid biosynthetic process; glycerophospholipid metabolic process; lipid metabolic process
Cellular component: membrane; peroxisomal membrane; peroxisome; cytosol; peroxisomal matrix
Genetic constraint (gnomAD): Loss-of-function variants: 9 observed, 27.48 expected, observed/expected ratio (o/e) 0.33, 90% interval 0.2 to 0.57. The upper end of that interval is the gene's LOEUF score, 0.57, which puts it in group 2 of 6, group 1 being the genes least tolerant of losing a copy. Missense variants: 307 observed, 380.42 expected, observed/expected ratio (o/e) 0.81, 90% interval 0.73 to 0.89. Synonymous variants: 140 observed, 140.77 expected, observed/expected ratio (o/e) 0.99, 90% interval 0.87 to 1.14.
Gene-disease validity (ClinGen):
ClinGen rates the evidence that GNPAT causes each of these diseases.
glyceronephosphate O-acyltransferase deficiency (autosomal recessive): Definitive. Any disorder of plasmalogen biosynthesis in which the cause of the disease is a mutation in the GNPAT gene.
Homologues: Orthologues: macaque GNPAT (98% identical), chimpanzee GNPAT (95% identical), rabbit GNPAT (91% identical), dog GNPAT (90% identical), pig GNPAT (88% identical), guinea pig GNPAT (88% identical), rat Gnpat (81% identical), mouse Gnpat (81% identical), tropical clawed frog gnpat (57% identical), zebrafish gnpat (54% identical), zebrafish gnpat2 (43% identical), Caenorhabditis elegans acl-7 (29% identical), and 1 more. Paralogues in human: GPAM (22% identical), GPAT2 (18% identical).
Diseases named in the same sentence as GNPAT in open-access papers:
GNPAT is named in the same sentence as 34 diseases in open-access papers, as found by Europe PMC text mining. Sharing a sentence is not in itself a finding about the gene and the disease. The quoted sentences say what the papers report.
rhizomelic chondrodysplasia punctata (16 papers, 2006 to 2025). Rhizomelic chondrodysplasia is a form chondrodysplasia punctata, a group of diseases in which the common characteristic is calcifications near joints at birth. "The GNPAT p.D519G variant has been identified as a cause of the peroxisomal disorder rhizomelic chondrodysplasia punctata (RCDP) 2, where it was shown to lead to a 70% decrease in enzymatic activity of GNPAT." (PMID 32766721, 2020). "Thus, we next investigated primary human fibroblasts from a patient with RCDP-2 (rhizomelic chondrodysplasia punctata type-2) harboring mutations in the enzyme glyceronephosphate O-acyltransferase (GNPAT) required for ether phospholipid synthesis via a PTS1/Pex5-dependent mechanism." (PMID 38397481, 2024). "Deficiencies in the peroxisomally localized ether lipid biosynthetic activities of glyceronephosphate O-acyltransferase (GNPAT) and alkylglycerone phosphate synthetase (AGPS) cause the human disease, rhizomelic chondrodysplasia punctata (RCDP)." (PMID 26685325, 2016). "Genetic deficiency or cellular mislocalization of one of the two peroxisomal enzymes that initiate plasmalogen biosynthesis, GNPAT and AGPS, results in the severe disorder rhizomelic chondrodysplasia punctata (RCDP)." (PMID 21679470, 2011). "Furthermore, loss-of-function mutations in four genes (PEX7, GNPAT, AGPS, and FAR1) that mediate peroxisomal synthesis of AAG, a necessary substrate for synthesis of plasmenyl-PE and plasmenyl-PC, result in rhizomelic chondrodysplasia punctata (RCDP)." (PMID 38582453, 2024).
hepatocellular carcinoma (7 papers, 2022 to 2026). A malignant tumor that arises from hepatocytes. "Dysregulation of peroxisomal enzymes such as AGPS and GNPAT has been shown to lead to the development of hepatocellular carcinoma." (PMID 40943222, 2025). "ACAT1-mediated acetylation of dihydroxyacetone phosphate acyltransferase (GNPAT) plays a key role in FASN stabilization to increase lipid synthesis in hepatocellular carcinoma." (PMID 36038892, 2022). "In hepatocellular carcinoma (HCC) models (Hep3B and HepG2 cells), inhibition of either GNPAT or USP30 significantly reduces DRP1 protein levels, triggering mitochondrial fusion and suppressing cancer cell proliferation and HCC progression." (PMID 40918504, 2025). "TRIM21 inhibits fatty acid (FA) synthesis by ubiquitination and degradation of fatty acid synthase (FASN) in hepatocellular carcinoma, and further studies found that the ubiquitination of FASN by TRIM21 could be inhibited by glyceronephosphate O-acyltransferase (GNPAT)." (PMID 36694250, 2023).
iron overload (3 papers, 2015 to 2020). "Using exome sequencing, we previously identified a variant (refSNP rs11558492) in the glyceronephosphate O-acyltransferase gene (GNPAT p.D519G), which was associated with increased iron overload in patients homozygous for the HFE p.C282Y mutation." (PMID 32766721, 2020). "The authors studied this polymorphism with regard to its effect on the severity of iron overload and found that 68% (15/22) of C282Y-homozygous males with high-iron phenotypes carried one allele and one male carried two alleles of GNPAT p.D519G." (PMID 26380265, 2015). "These in vivo data argue against the hypothesis that GNPAT is a genetic modifier that independently regulates iron metabolism in order to exacerbate the iron‐overload phenotype in patients with HFE‐linked haemochromatosis." (PMID 32108988, 2020). "Exome sequencing has identified the glyceronephosphate O-acyltransferase (GNPAT) gene as a genetic modifier of iron overload in hereditary hemochromatosis (HH)." (PMID 32766721, 2020).
peroxisomal biogenesis disorders (3 papers, 2020 to 2025). "RCDP is a recessive peroxisomal disease caused by variants in five genes: AGPS, FAR1, GNPAT, PEX5, and PEX7, which encode alkylglycerone phosphate synthase, fatty alcohol reductase 1, glycerone-phosphate O-acyltransferase, and the peroxisomal biogenesis factors 5 and 7, respectively." (PMID 40394457, 2025).
chronic obstructive pulmonary disease (2 papers, 2025). A chronic and progressive lung disorder characterized by the loss of elasticity of the bronchial tree and the air sacs, destruction of the air sacs wall, thickening of the bronchial wall, and mucous accumulation in the bronchial tree. "Our previous study revealed the role of glycerol phosphate O‐acyltransferase (GNPAT) in regulating chronic obstructive pulmonary disease (COPD)." (PMID 40709564, 2025).
haemochromatosis (2 papers, 2020). "Therefore, an open question is whether the GNPAT p.D519G variant plays a direct role in iron metabolism or whether this variant functions in regulating HFE‐linked haemochromatosis." (PMID 32108988, 2020). "In conclusion, our results indicate that GNPAT does not play an essential role in iron metabolism or in the development of HFE‐linked haemochromatosis in an in vivo mouse model." (PMID 32108988, 2020).
hemochromatosis (2 papers, 2016 to 2020). A disorder of iron metabolism characterized by a triad of HEMOSIDEROSIS; LIVER CIRRHOSIS; and DIABETES MELLITUS. "Subsequently, a number of studies either supporting or opposing the role of GNPAT as a modifier of HFE hemochromatosis have been reported." (PMID 32766721, 2020).
Alzheimer disease (1 paper, 2021). A progressive, neurodegenerative disease characterized by loss of function and death of nerve cells in several areas of the brain leading to loss of cognitive function such as memory and language. "The method was used in this study to evaluate the time-dependent changes of Pls molecular species in the hippocampal brain tissues of an Alzheimer’s disease model mouse and correlate the changes with ROS and GNPAT levels." (PMID 34942905, 2021).
epilepsy (1 paper, 2025). A brain disorder characterized by episodes of abnormally increased neuronal discharge resulting in transient episodes of sensory or motor neurological dysfunction, or psychic dysfunction. "Group 2—Intermediate epilepsy/metabolic disorders (Ion-channel and neuronal-excitability phenotype): This group comprised patients harboring variants in SCN2A, PAH, IQSEC2, and GNPAT." (PMID 41300846, 2025).
Epileptic encephalopathy (1 paper, 2025). A condition in which epileptiform abnormalities are believed to contribute to the progressive disturbance in cerebral function. "Pathogenically, SCN2A variants alter voltage-gated sodium channel activity, leading to early infantile epileptic encephalopathy, whereas PAH and GNPAT variants disrupt amino acid and peroxisomal metabolism, respectively." (PMID 41300846, 2025).
glioblastoma (1 paper, 2023). The most malignant astrocytic tumor (WHO grade IV). "According to the GEPIA database, the expression level of DHAPAT/GNPAT in glioblastoma tumors does not differ from that of healthy brain tissue, and the expression of this gene in glioblastoma does not affect patient prognosis." (PMID 37046844, 2023).
Hepatic steatosis (1 paper, 2020). Steatosis is a term used to denote lipid accumulation within hepatocytes. "In fact, decreased levels of hepatic glyceronephosphate O-acyltransferase, which is a key peroxisomal enzyme for the synthesis of ether-linked phosphoglycerolipids, have been observed in a rat model of hepatic steatosis." (PMID 32878279, 2020).
liver cancer (1 paper, 2024). An epithelial or non-epithelial malignant neoplasm that arises from the liver. "In liver cancer, ACAT1 promotes lipid metabolism and tumor occurrence by stabilizing FASN through the acetylation of GNPAT." (PMID 39247186, 2024).
lymphoma (1 paper, 2020). A malignant (clonal) proliferation of B- lymphocytes or T- lymphocytes which involves the lymph nodes, bone marrow and/or extranodal sites. "In addition to AGPS, elevated expression of FAR1, FAR2, and GNPAT, all of which are involved in ether phospholipid biosynthesis, was observed in aggressive lymphoma cells derived from lymphoma patients who were refractory to oxidative stress-inducing therapy." (PMID 32674458, 2020).
male infertility (1 paper, 2013). The inability of the male to effect fertilization of an ovum after a specified period of unprotected intercourse. "In addition, a depletion of ether lipids also causes male infertility in PEX7 and GNPAT knockout mice." (PMID 24319432, 2013).
melanoma (1 paper, 2023). A malignant, usually aggressive tumor composed of atypical, neoplastic melanocytes. "Moreover, GNPAT significantly enhanced the growth-suppressing effects of CDDO-Me (an antitumor agent) and induced apoptosis in melanoma cells." (PMID 38041059, 2023).
ovarian carcinoma (1 paper, 2024). A malignant neoplasm originating from the surface ovarian epithelium. "In order to further analyse the importance of the ether lipid synthesis gene, GNPAT and AGPS were compared side by side under different ovarian cancer conditions." (PMID 39700026, 2024).
cancer (4 papers, 2020 to 2025). A tumor composed of atypical neoplastic, often pleomorphic cells that invade other tissues. "It has been reported that GNPAT can recruit the deubiquitinase ubiquitin‐specific protease 30 (USP30) to stabilize the DRP1 protein in cancer." (PMID 40709564, 2025). "The regulatory relationships among GNPAT, USP30, and DRP1 were previously reported in cancer." (PMID 40709564, 2025).
tumor (4 papers, 2020 to 2024). "ACAT1 overexpression enhanced tumor growth in HCC xenografts and GNPAT deletion could attenuate ACAT1-induced HCC growth, and ACAT1 overexpression with GNPAT inhibition diminish fatty acid synthesis and lipogenesis." (PMID 38720812, 2024). "Precisely, ACAT1-mediated GNPAT acetylation could inhibit GNPAT degradation by repressing TRIM21-mediated GNPAT ubiquitination, ultimately promoting tumor growth in HCC xenografts." (PMID 38720812, 2024). "Therefore, it cannot be ruled out that the tumor inflammatory component could account for the GNPAT mRNA levels observed in this study." (PMID 32443825, 2020).
skeletal dysplasia (1 paper, 2025). Any Mendelian diseases that affects growth and development of the skeleton. "GNPAT is associated with autosomal recessive Rhizomelic chondrodysplasia punctata, a disorder characterized by craniofacial abnormalities, skeletal dysplasia, and central nervous system involvement." (PMID 40634996, 2025).
GNPAT also shares sentences with these, for which no sentence is quoted: rhizomelic chondrodysplasia punctata type 2 (3 papers); Azoospermia (1); cataract (1); colon cancer (1); infertile (1); Intellectual disability (1); metabolic disorders (1); neurodevelopmental disorder (1); neutropenia (1); Obesity (1); porphyria (1); retinal degeneration (1); rhizomelic chondrodysplasia punctata type 1 (1); vertebral disorder (1).